DDR2 (discoidin domain receptor tyrosine kinase 2)
Diseases named in the same sentence as DDR2 in open-access papers (continued):
Sharing a sentence is not in itself a finding about the gene and the disease.
cancer (111 papers, 2007 to 2026). A tumor composed of atypical neoplastic, often pleomorphic cells that invade other tissues. "DDR2 alterations (overexpression, amplification, and mutations) are known to drive more aggressive phenotypes in several cancer types." (PMID 39459560, 2024). "Consistent with this notion, a recent study on cancer‐associated fibroblasts show that DDR2 activation is required for full activation of β1 integrins." (PMID 38538106, 2024). "A recent study further suggested that DDR2 regulates the integrin‐mediated mechanotransduction functions of cancer‐associated fibroblasts." (PMID 38538106, 2024). "For example, overexpression of DDR1 enhances integrin matrix adhesion in human embryonic kidney cells and in human and mouse fibroblasts, and high levels of DDR2 enhance integrin activation in cancer-associated fibroblasts in mice." (PMID 37405383, 2023). "Using patient-derived omentum cancer-associated fibroblasts from high-grade serous ovarian cancers (Om-CAFs), we show that DDR2-depletion leads to decreased expression of POSTN." (PMID 35884543, 2022). "In cancer associated fibroblasts, DDR2 was shown to activate Rap1 which increases talin recruitment to integrin complexes and in turn increases integrin β1 activation." (PMID 35309920, 2022). "In fact, bioinformatics analyses corroborate that DDR2 signaling in BC is widely connected to cancer-associated pathways, apart from those related to ECM interaction." (PMID 35711892, 2022). "Consistently, the gene expression of collagen I receptors, linked to active tissue remodeling and cancer, including DDR2, ITGA2, ITGA10, ITGA11 and ITGB1 was higher in OS compared to RMS, whilst DDR1 expression was higher in RMS tumors." (PMID 35957513, 2022). "Third, although DDR2 has been implicated in EMT in multiple cancer types, we observed that alteration of DDR2 expression by ectopic expression or knockdown did not alter the EMT phenotype in the HMLE TF-driven models or multiple TNBC cell models." (PMID 36713812, 2022). "Driver mutations, including RET, CBL, and DDR2 gene mutations, were identified in the hypermutated cancers." (PMID 34503126, 2021). "There were more FLT3, FGFR1, and AKT1 mutations (p-value < 0.05) in nonhypermutated cancers, while there were more RET, CBL, and DDR2 mutations (p-value < 0.05) in hypermutated cancers." (PMID 34503126, 2021). "While activation of DDRs is required for normal development, studies have reported differential expression and mutations of DDR1 and DDR2 in several cancers." (PMID 27014069, 2016). "A number of cancer-associated DDR2 point mutations were recently identified at low frequency through cancer genome sequencing studies in lung SCC." (PMID 23822953, 2013). "DDR receptors are implicated in many developmental and physiological roles, such as mammary gland development (for DDR1) or proper bone growth (for DDR2), while their deregulation may underlay certain types of cancer." (PMID 34716856, 2022). "DDR2 overexpression has been linked to progression of different cancer types, including BC." (PMID 35711892, 2022). "RET, CBL, and DDR2 driver mutations might represent potential response markers in hypermutated cancers." (PMID 34503126, 2021). "In addition, we identified RET, CBL, and DDR2 driver mutations as potential response markers in hypermutated cancers." (PMID 34503126, 2021). "DDR1 and DDR2 dysregulation has been linked to multiple forms of cancer." (PMID 34207360, 2021). "DDR2 influences mechanotransduction by cancer associated fibroblasts." (PMID 31144616, 2019). "Furthermore, it was found that the abnormal expression of DDR2 implicated in cancer progression and a poor prognosis." (PMID 26362312, 2015). "Moreover, DDR2 mutations have been noted in several cancer specimens including in NSCLC (R105S, H136H and N456S)." (PMID 24885564, 2014).
cancer (continued). "Notably, the receptors can function both independently and synergistically; for instance, DDR2 in cancer-associated fibroblasts regulates integrin-mediated mechanosignaling to promote metastasis, while in other contexts, both receptors activate distinct survival pathways." (PMID 41492134, 2026). "Furthermore, previous research has associated several adhesion molecules on cancer-associated fibroblasts, including syndecan-1 and DDR2, with the regulation of matrix organization and stiffness in BC and should be investigated on the HLFs conditioned via CM or EV-enriched solutions." (PMID 32429591, 2020). "Strikingly, DDR2-driven signaling pathways active in physiological contexts are expected to mediate more than those known so far also in pathological contexts like cancer." (PMID 41492134, 2026). "Stage-stratified correlation analysis of fourteen pathway genes revealed profound divergence between DDR1 and DDR2; DDR1 correlations remained weak across all stages, while DDR2 correlations strengthened 2.59-fold from normal to carcinoma." (PMID 41828724, 2026). "The DDR family (DDR1/DDR2) can be activated by various collagen types, influencing diverse cancer cell behaviors." (PMID 40563472, 2025). "While DDR2 plays an important role in normal development by regulating cell proliferation and ECM matrix remodeling, an elevated expression of DDR2 has been shown to correlate with increased metastasis in various cancers." (PMID 39459560, 2024). "Dysregulated DDR2 expression has been identified in various cancer types, making it as a promising therapeutic target." (PMID 38538106, 2024). "DDR2 is consistently overexpressed in metastatic and recurrent cancer, which contributes to the establishment of fibroblastic phenotypes of cancer cells." (PMID 37568677, 2023). "We suggest that the most important reason lies in the interaction between DDR2-/- HSCs and cancer cells." (PMID 37007062, 2023). "Considering the capacity of YAP/TAZ and DDR2 to boost both ferroptosis and metastasis, instigating ferroptosis emerges as a potentially effective strategy to tackle cancer cells during the earliest phase of metastasis." (PMID 37568677, 2023). "A recent study reported that peptides containing the DDR2 functional domain or JM2 domain can be effectively delivered to cancer cells through a system based on AuNP-DNA aptamer conjugates." (PMID 36741760, 2023). "The peptide containing the DDR2 functional domain inhibits the proliferation and invasion of cancer cells mediated by DDR2 activation." (PMID 36741760, 2023). "When DDR2 binds to extracellular collagen, it triggers SHP-2, SRC, and mitogen-activated protein kinase signaling; hence, DDR2 mutations induce cancer cell proliferation, differentiation, and metastasis." (PMID 36499051, 2022). "While DDR1 and DDR2 have been linked to cancer progression and metastasis, a downregulation of DDR1 and concomitant upregulation of DDR2 has been explicitly observed in EMT." (PMID 36713812, 2022). "Some collagens also bind and activate receptor tyrosine kinases discoidin domain receptors (DDR1 and DDR2) that are thought to mediate metastases and cancer aggressiveness." (PMID 35008401, 2022). "As a plasma membrane bound receptor, DDR2 presents as an attractive therapeutic target for a variety of cancers, inflammatory conditions, as well as brain and renal disease." (PMID 35406381, 2022). "On the one hand, KEGG 2019 Human Database indicated that DDR2 was predominantly related to ECM interplay and cell adhesion, two features directly linked with DDR tyrosine kinase family, along with cancer signaling pathways." (PMID 35711892, 2022).
cancer (continued). "Aside from the main role of DDR1 and DDR2 in human cancer, they are also involved in other disorders such as inflammation, tissue fibrosis and atherosclerosis, and neurodegenerative diseases." (PMID 34207360, 2021). "We also detected the expression level of COL11A1, integrin α1β1 and DDR2 in cancer cell total lysates by western blotting to assess the knockdown efficiency of si-COL11A1, siα1β1 and siDDR2." (PMID 33531986, 2021). "Discoidin domain receptors (DDR1 and DDR2) are the collagen receptors of the family tyrosine kinases, which play significant role in the diseases like inflammation, fibrosis and cancer." (PMID 34145346, 2021). "Patients with DDR2 cancer had a higher DDR score and benefited less from traditional treatment than patients with DDR1 cancer, but the DDR2 type was significantly related to a longer survival time with immunotherapy." (PMID 34335575, 2021). "DDR2 was involved in hypoxia-induced cancer metastasis by accelerating migration, invasion and EMT of BC cells." (PMID 33439992, 2021). "These included the following genes known for their association with cancer: BRAF (V600E) and PIK3CA (E545K), both harboring hotspot mutations and three other possible driver genes, SDHC (H127R), DDR2 (R668C), and FANCD2 (C1130Y)." (PMID 34301805, 2021). "There are not many studies that focused on the analysis of the impact of DDR1 and DDR2 within the same cancer, although, very often, both receptors are expressed." (PMID 33917302, 2021). "Herein, we showed that COL11A1 is conducted by integrin α1β1 and DDR2 to mediate cancer cell proliferation and activate AktSer473 signal transduction." (PMID 33531986, 2021). "Since their discovery more than 20 years ago, the DDR1 and DDR2 collagen receptors are considered critical regulators of cancer invasion." (PMID 32117772, 2020). "The first evidence of DDR2 oncogenic role in human cancer came from its alteration in squamous lung cancer." (PMID 32117772, 2020). "Some studies have shown that the targeting of DDR2 by FDA-approved kinase inhibitors including dasatinib, imatinib, nilotinib, and ponatinib can suppress the proliferation of this gene in mutated cancer cell lines." (PMID 30048458, 2018). "It will be interesting to identify subsets of different cancers that depend most on HORMAD1 for DNA damage tolerance (perhaps including tumors driven by co-amplified DDR2 oncogene)." (PMID 30333500, 2018). "Because collagen is known to stimulate EMT1, 13, 14, DDR2 function in EMT during cancer progression cannot be ignored." (PMID 28754957, 2017). "Accordingly, these results suggested that DDR2 expression on a stiff matrix drives cancer cell proliferation and expression of a set of EMT-related genes." (PMID 28754957, 2017). "Cumulatively, these results suggest that the role of collagen and DDRs in MT1-MMP regulation in cancer cells is different from that in fibroblasts, and the role of DDR2 in MT1-MMP activation seems to be limited to stromal fibroblasts." (PMID 28270508, 2017). "DDR2, a receptor tyrosine kinase, is considered to be involved in the progression of many cancer types." (PMID 26362312, 2015). "Our study demonstrated that DDR2 has an oncogenic role in HCC tumorigenesis by facilitating cancer cell invasion, migration and epithelial–mesenchymal transition via activating ERK signaling and stabilizing SNAIL1." (PMID 26362312, 2015). "Our current work revealed that DDR2 has an oncogenic role in hepatocarcinogenesis by facilitating cancer cell invasion, migration and EMT via activating ERK2 and stabilizing SNAIL1." (PMID 26362312, 2015). "The altered expression patterns of DDR2 mRNA expression have been reported in multiple types of human cancer, including NSCLC." (PMID 24885564, 2014). "Inhibition of cancer cell growth by fibrillar collagen is well documented and our results are consistent with published data indicating that DDR2 inhibits cancer cell proliferation when challenged with fibrillar collagen." (PMID 23822953, 2013).
cancer (continued). "DDR2 also contributes to disease progression, including hepatic fibrosis, osteoarthritis and cancer." (PMID 23822953, 2013). "The specific role of DDR2 in neutrophils’ regulation of cancer cell biology remains unclear and warrants deeper exploration." (PMID 40563472, 2025). "As explored in "PAPP-A in TNBC: role in Epithelial-Mesenchymal Transition (EMT)" section of this review, elevated phosphorylated DDR2 and Snail are known drivers of cancer progression and EMT; and experimentally correlated with significantly higher invasion and migration." (PMID 38395880, 2024). "As such, DDR2 could represent an important therapeutic target and have a significant impact on cancer progression." (PMID 39459560, 2024). "DDR2 is a strong prognostic marker of poor survival in various cancers and adult tumors." (PMID 39459560, 2024). "Despite these studies, how DDR2 regulates cancer cell behavior is incompletely understood." (PMID 38538106, 2024). "Similarly, overexpression of the transmembrane 2 (JM2) domain blocks the activation of DDR2, thereby reducing the proliferation and invasion of cancer cells in vitro." (PMID 36741760, 2023). "Therefore, TM-JM1/2 peptide loaded on the AuNP-Apt conjugate can be a useful strategy for DDR2 positive cancer treatment." (PMID 36741760, 2023). "Through this AuNP-Apt-based system, intracellular delivery of TM-JM1/2 peptide could effectively inhibit collagen-induced DDR2 activation and reduce the proliferation and invasion of cancer cells." (PMID 36741760, 2023). "Interestingly, DDR2 is mainly expressed in HSCs, although it is also seen in hepatocytes or cancer cells." (PMID 37007062, 2023). "This suggests that the DDR2 signaling pathway may modulate the metabolic status of cancer cells through regulating the expression of certain metabolism enzymes or through signaling changes that impact enzymatic activity through posttranslational modification." (PMID 36713812, 2022). "It has been shown previously that DDR2 promotes metastasis in numerous cancers." (PMID 35884543, 2022). "When combined with dasatinib in MCF10A-WT and CDH1−/− cells, MK2206 exhibited synergy, indicating that the simultaneous targeting of SRC, DDR2 and AKT may be effective in specifically targeting E-cadherin-deficient cancer cells." (PMID 35406381, 2022). "DDR2 overexpression has been related to poor prognosis in several cancer types, including BC." (PMID 35711892, 2022). "High expression of DDR2 leads to increased metastasis in various cancers." (PMID 35884543, 2022). "The critical role of DDR2 in cancer metastasis has been well established." (PMID 36713812, 2022). "Inhibiting DDR1 or DDR2 with nilotinib, dasatinib, or other non‐approved inhibitors was shown to decrease tumorigenicity, invasion, or metastasis of several carcinomas." (PMID 34957688, 2022). "In addition, a recent study emphasizes the clinical significance of DDR2 as a potential marker for cancers, showing that targeting DDR2 potentiates anti-PD-1 clinical response." (PMID 34065317, 2021). "Importantly, this group of fibroblast cells expressed the markers for cancer‐associated fibroblasts (CAFs) including ACTA2 (encoding α‐SMA), PDGFRA, PDGFRB, DDR2, FAP, and CAV1." (PMID 34459128, 2021). "Therefore, COL11A1/integrinα1β1/DDR2 signaling to inhibit the apoptotic process through PI3K/Akt has been demonstrated in other cancer types 33-35." (PMID 33531986, 2021). "DDR2 has also been shown to promote migration and invasion in many cancers." (PMID 33917302, 2021). "Interestingly, activation of DDR2 can induce production of MMPs, and therefore, DDR2 is recognized as playing a very important role in fibrosis and cancer." (PMID 34956435, 2021). "Discoidin domain-containing receptor 2 (DDR2) is another miR-182 target gene that mediates cell interactions of extracellular matrix (ECM) so may contribute to cancer cell proliferation and migration." (PMID 34721577, 2021).
cancer (continued). "In addition, the silencing of DDR2 expression markedly decreased LPA-induced cancer cell invasive foci formation and growth on 3D Matrigel and 3D Matrigel-coated transwell chambers." (PMID 34065317, 2021). "Consistently, both DDR1 and DDR2 are expressed in cancers of epithelial and mesenchymal origin." (PMID 32047176, 2020). "DDR2 fusions were also detected in another nine samples from five different cancer types, which could be treated similarly given sufficient DDR2 overexpression." (PMID 29617662, 2018). "However, in our analysis of TCGA data we also noticed that HORMAD1 is often co-expressed with DDR2 (encoding a collagen-binding receptor tyrosine kinase), a known oncogenic driver in NSCLC and other cancers." (PMID 30333500, 2018). "Therefore, the downregulation of c-Myb resulted in a decrease of DDR2 expression, leading to inhibition of cancer progression and downregulation of EMT marker genes." (PMID 28754957, 2017). "Moreover, clinical studies on DDR1 and DDR2 expression and the outcome of several cancer pathologies found a correlation between the expression of these receptors, metastasis, and a reduced survival." (PMID 27014069, 2016). "However, collagen inhibits cancer cell growth through DDR2-dependent cell cycle arrest in some kinds of cancer." (PMID 27528792, 2016). "These new insights suggest that DDR1 and DDR2 are new potential targets in cancer therapy." (PMID 27014069, 2016). "DDR2 have previously been reported to be involved in various human diseases, including cancers." (PMID 24885564, 2014). "To investigate whether DDR2 mutation could have a direct functional effect in facilitating lung SCC cell migration and invasion, we evaluated cancer cell invasion through matrigel and migration through wound healing and transwell assays." (PMID 24885564, 2014). "Among these genes DDR2 has previously shown to mediate contact inhibition of cancer cells." (PMID 21151926, 2010). "These insights could lay the foundation for exploring a specific understanding of the cellular contexts that dictate the phenotypic output of DDR2 regulation and for uncovering critical metabolic targets that mediate the protumorigenic effects of DDR2 in cancer cells." (PMID 36713812, 2022). "Moreover, DDR2 was reported to induce cancer invasion via matrix metalloproteinase expression." (PMID 34065317, 2021). "As such DDR2 could represent an important therapeutic target to prevent cancer metastasis." (PMID 31144616, 2019). "Finally, the authors review pharmacological approaches to inhibit DDR1 and DDR2, which might represent valuable targets for anti-cancer therapies." (PMID 27148054, 2016). "Thus, inhibition of DDR2 function using a JM2-containing peptide may be a useful strategy for the treatment of DDR2-positive cancers." (PMID 27014069, 2016). "Based on the overall data, we would like to conclude that the DDR2 gene mutation is detectable in the CNS metastases of NSCLC, and analysis of gene profile in cancer patients may extend the scope of molecularly targeted therapies used both in patients with primary and metastatic NSCLC." (PMID 25173530, 2014). "DDR2 inhibitors suppress HCC proliferation both in vivo and in vitro and promote cancer cell apoptosis." (PMID 40563472, 2025). "Based on our results, we propose that the ECM could activate DDR2 signaling and mechanosensing in cancer cells to orchestrate their cell fate through distinct mechanisms, with or without involving gene expression, thus providing novel mechanistic insights into cancer progression." (PMID 38538106, 2024). "Recently, discoidin domain receptor tyrosine kinase 2 (DDR2), a non‐typical collagen receptor that is dysregulated in various cancer types, has emerged as a key signaling molecule in carcinogenesis." (PMID 38538106, 2024). "Here, we discussed the roles of DDR1 and DDR2 in premalignant liver diseases, primary HCC and metastatic liver cancer derived from several other cancer types." (PMID 37007062, 2023).